ZNF366 (zinc finger protein 366)
Description:
Has transcriptional repression activity. Acts as a corepressor of ESR1; the function seems to involve CTBP1 and histone deacetylases.
Synonyms: DC-SCRIPT; FLJ39796; DCSCRIPT
Tractability: PROTAC: ubiquitination databases record sites on it.
Gene: Protein-coding gene on chromosome 5 (72,439,903 to 72,507,410, reverse strand). Ensembl gene ENSG00000178175.
Subcellular location: Nucleus
Subcellular location (Human Protein Atlas): Nucleoplasm
Gene Ontology:
Molecular function: nuclear estrogen receptor binding; protein binding; transcription corepressor activity; DNA-binding transcription factor activity; RNA polymerase II cis-regulatory region sequence-specific DNA binding
Biological process: negative regulation of intracellular estrogen receptor signaling pathway; negative regulation of transcription by RNA polymerase II; response to estrogen
Cellular component: nucleoplasm; nucleus
Genetic constraint (gnomAD): Loss-of-function variants: 21 observed, 50.29 expected, observed/expected ratio (o/e) 0.42, 90% interval 0.29 to 0.6. The upper end of that interval is the gene's LOEUF score, 0.6, which puts it in group 2 of 6, group 1 being the genes least tolerant of losing a copy. Missense variants: 987 observed, 1,030.7 expected, observed/expected ratio (o/e) 0.96, 90% interval 0.91 to 1.01. Synonymous variants: 421 observed, 421.47 expected, observed/expected ratio (o/e) 1, 90% interval 0.92 to 1.08.
Homologues: Orthologues: chimpanzee ZNF366 (99% identical), macaque ZNF366 (98% identical), pig ZNF366 (87% identical), guinea pig ZNF366 (86% identical), mouse Zfp366 (86% identical), rat Zfp366 (85% identical), rabbit ZNF366 (84% identical), dog ZNF366 (71% identical), tropical clawed frog znf366 (57% identical), zebrafish znf366 (49% identical), Drosophila melanogaster CG10631 (25% identical), Drosophila melanogaster CG11696 (15% identical), and 1 more. Paralogues in human: ZNF710 (42% identical), ZNF865 (17% identical), ZNF667 (15% identical), ZNF671 (14% identical), ZNF662 (11% identical), ZNF212 (11% identical), ZNF783 (10% identical).
Diseases named in the same sentence as ZNF366 in open-access papers:
ZNF366 is named in the same sentence as 10 diseases in open-access papers, as found by Europe PMC text mining. Sharing a sentence is not in itself a finding about the gene and the disease. The quoted sentences say what the papers report.
breast carcinoma (2 papers, 2010 to 2015). "ZNF366 could also act as a tumor suppressor in breast cancer development." (PMID 25722978, 2015).
endometriosis (2 papers, 2015 to 2020). The growth of functional endometrial tissue in anatomic sites outside the uterine body. "The genetic variant rs4703908 located near ZNF366 has been linked to an increased risk of endometrioma and deep infiltrating endometriosis." (PMID 32370117, 2020). "ZNF366 has been proposed as a new contributor to the development of endometriosis, since four SNPs (rs227849, rs4703908, rs2479037, and rs966674) were found to be significantly associated with endometrioma risk." (PMID 32370117, 2020).
alcohol dependence (1 paper, 2018). Physical and psychological dependence on alcohol. "The top two loci, PTP4A1-PHF3-EYS and ZNF366 have been previously associated with alcohol dependence, alcohol intake (dbGaP: phs000342) and glucocorticoid receptor function." (PMID 30571770, 2018). "However, gene-based tests identified a genome-wide significant gene, ZNF366, a negative regulator of glucocorticoid receptor function implicated in alcohol dependence (p = 1.48x10-7; Bonferroni-corrected significance threshold p < 2.79x10-6)." (PMID 30571770, 2018).
asthma (1 paper, 2020). "The PBMC data show that cytosolic acyl coenzyme A thioester hydrolase 7 (ACOT7) gene might act in concert with another candidate gene, Zinc Finger Protein 366 (ZNF366) gene, to jointly influence the risk of asthma." (PMID 31932625, 2020).
prostate carcinoma (1 paper, 2017). A carcinoma that arises from epithelial cells of the prostate gland. "Furthermore, as PCa is hormonally driven, the crosstalk between AR and VDR in prostate cancer was previously investigated, reporting that AR activation inhibits VDR-mediated transcription through the activity of different coregulatory proteins such as prohibitin, ARA70, or ZNF366." (PMID 28811844, 2017).
Sepsis (1 paper, 2022). Sepsis is defined as life-threatening organ dysfunction caused by a dysregulated host response to infection. "In this study, WGCNA and DiffCorr were employed to find out novel hub genes including ZNF366, ZMYND11, SVIP and UBE2H, and we proposed for the first time their causative factors during sepsis progression." (PMID 35401666, 2022).
tumor (3 papers, 2010 to 2016). "ADRA1A and ZNF366 have proliferation regulatory functions that limit tumor cells from forming tumors/metastases in response to stimulators." (PMID 27136531, 2016).
ZNF366 also shares sentences with these, for which no sentence is quoted: breast tumors (2 papers); colorectal adenocarcinoma (1); invasive breast carcinoma (1).